MMP2 (matrix metallopeptidase 2)
Diseases named in the same sentence as MMP2 in open-access papers (continued):
Sharing a sentence is not in itself a finding about the gene and the disease.
periodontitis (continued). "Carvedilol (10 mg/kg) treatment reduced the levels of COX-2, MMP-2, MMP-9, RANK-L, and RANK expression in the periodontium of rats subjected to experimental periodontitis." (PMID 23843954, 2013). "The strong interactions of EGCG with ESR1, MMP2, MMP9, MMP13, and STAT1 support its potential to modulate MMP activity and reduce extracellular matrix degradation, thereby mitigating tissue destruction in periodontitis." (PMID 41009706, 2025). "Higher GCF MMP-2 levels were reported in periodontitis patients with DM compared to non-DM individuals." (PMID 38614881, 2024). "In this study, we aimed to (i) detect Td-dentilisin and MMP-8 immunoexpression levels in gingival tissue samples of patients with periodontitis compared with periodontally healthy gingivae to (ii) assess the MMP-8, MMP-2, MMP-7, TIMP-1, and IL-1β mRNA expressions in the diseased vs. healthy gingiva." (PMID 38786309, 2024). "In another induced periodontitis in a diabetic rat experiment, Cu reduced the infiltration of PMN and monocytes, the degradation of periodontal collagen fibers—and decreased IL-1β, IL-6, TNF-α MMP-9 and MMP-2, MMP-8 levels." (PMID 38793109, 2024). "The plotted ROC curves showed a good predictor value for the MMP-9/TIMP-1 ratio, the (MMP-8 + MMP-9)/TIMP-1 ratio and the MMP-8 + MMP-9 sum (as top three), followed by the MMP-8/TIMP-1 ratio, HGF, MMP-2, and OPG for differentiation of periodontitis versus gingivitis conditions (AUC ≥ 0.85)." (PMID 33742017, 2021). "In another study on GCF from periodontitis patients, both forms of MMP-2 were only detected in GCF from patients but not in healthy subjects." (PMID 32809076, 2021). "The plotted ROC curves showed a good predictor value of the MMP-9/TIMP-1 ratio, (MMP-8 + MMP-9)/TIMP-1 ratio, and HGF (as top three), followed by the MMP-9, MMP-2, MMP-8 + MMP-9 sum and the MMP-8/TIMP-1 ratio, for differentiation of periodontitis versus health conditions (AUC ≥ 0.95)." (PMID 33742017, 2021). "Cluster 7 grouped 28 genes with positive correlations to RANKL only in periodontitis tissues, and strong negative correlations to CTSK in periodontitis and MMP2 in both healthy and periodontitis samples." (PMID 27486459, 2016). "The periodontium of rats presenting with experimental periodontitis receiving no treatment (EPD) showed marked immune-staining for to the following markers: MMP-2, MMP-9, COX-2, RANK-L, and RANK compared to periodontium staining profile of the saline group." (PMID 23843954, 2013). "Furthermore, the periodontium of rats with periodontitis and treated with a high-dose of Atorvastatin had even lower levels of COX-2, as well as MMP-2, MMP-9, RANK-L and RANK." (PMID 24130702, 2013). "Multiple neutrophil-derived proteolytic enzymes have been shown to be elevated in periodontitis compared to healthy controls, including myeloperoxidase (GCF) and matrix metalloproteinases (e.g., MMP-2 and MMP-9) whose major source in the periodontium is the neutrophil." (PMID 23843954, 2013). "Also, they revealed that MMP-2 mRNA was virtually absent in the periodontitis groups, but present in some gingivitis-affected tissues and healthy controls; MMP-9 transcripts were more frequently detected in periodontitis samples." (PMID 38474009, 2024). "In addition to this, MMP-1, MMP-2, MMP-10, and MMP-12 were also observed to be significantly increased in patients with OSCC compared to healthy patients and patients with benign oral masses (OBM) and mild chronic periodontitis (CPD)." (PMID 33892690, 2021). "In addition, in periodontitis, aberrant activation of the Wnt/β-catenin signaling pathway could inhibit the EMMPRIN/MMP-2/ 9 axis." (PMID 34227646, 2021). "MMP-2 -753C>T and MMP-9 -1562C>T polymorphisms may not be associated with periodontitis risk in overall analysis." (PMID 31497543, 2019). "MMP-2-753C>T and MMP-9-1562C>T polymorphisms may not be associated with risk of periodontitis in overall population." (PMID 31497543, 2019).
periodontitis (continued). "Furthermore, a previous study also showed that myricetin decreased the mRNA expression and enzyme activity of matrix metalloproteinase-1 (MMP-1), MMP-2, and MMP-8, which were involved in the inflammatory progression in periodontitis in the human gingival fibroblasts (HGF)." (PMID 27011174, 2016). "Chlorhexidine, the most widely used adjuvant in the treatment of periodontitis, acts as a non-specific MMPI through chelation of calcium and zinc cations, inhibiting MMP-2, MMP-8, and MMP-9." (PMID 41002732, 2025). "This study evaluated the gene expression of IL-1ß, IL-6, TNF-α, MMP-1, MMP-2, MMP-8, MMP-9, TIMP-1, and TIMP-2 in the gingival tissue of individuals with periodontitis or peri-implantitis compared to individuals without periodontal or peri-implant disease." (PMID 33291232, 2020). "Cluster 8 genes (n = 18) were similar to cluster 7 with negative correlations to MMP2 and CTSK in periodontitis and health, as well as negative correlations with MMP9 in periodontitis tissues." (PMID 27486459, 2016). "However, Gonçalves and colleagues revealed that MMP transcripts (for MMP-1, MMP-2, MMP-9, and MMP-13) found in gingiva samples were not significantly different in patients affected by gingivitis, chronic periodontitis, and aggressive periodontitis." (PMID 38474009, 2024).
pulmonary fibrosis (66 papers, 2005 to 2026). Chronic progressive interstitial lung disorder characterized by the replacement of the lung tissue by connective tissue, leading to progressive dyspnea, respiratory failure, or right heart failure. "High levels of MMP-2 and MMP-9 in diseases with lung fibrosis and the progression of fibrosis in mice with MMP-2 deficiency are literature data supporting this idea." (PMID 39860018, 2025). "This study showed that SIN inhibited the abnormal expression of TIMP-1 and MMP-2/9 caused by pulmonary fibrosis and improved the physiological homeostasis of ECM." (PMID 38730387, 2024). "MMP-2, which is synthesized by structural cells, including endothelial cells, epithelial cells, and fibroblasts, is associated with impaired tissue remodeling, thus leading to pathological collagen deposition and pulmonary fibrosis." (PMID 37763673, 2023). "Adrenergic-stimulated histological lung fibrosis is associated with a remarkable increase in TGFβ1, collagen I, MMP-2 and TIMP-2 mRNA expression, suggesting a link between adrenergic stimulation, the up-regulation of ECM molecules and the promotion of fibrotic processes." (PMID 34071777, 2021). "Enhanced activity of MMP2 or MMP9 is associated with bleomycin-induced pulmonary fibrosis, sustained lung inflammation following endotoxin exposure, interstitial fibrosis following repeated endotoxin exposure, lung injury following exposure to ozone and subacute hyperoxia." (PMID 31842927, 2019). "Moreover, MMP-2 was upregulated in a lipopolysaccharide-induced lung fibrosis model and was considered to cause damage to the lung extracellular matrix as well as be associated with the development of lung fibrosis." (PMID 37675120, 2023). "Resveratrol effectively inhibits alveolar epithelial cell senescence and ameliorates pulmonary fibrosis, likely by targeting key senescence-associated pathways (e.g., SERPINE1, MMP2, IL-6)." (PMID 41383484, 2025). "Increased protein abundance of MMP2 was found either in lung fibrosis animal models or fibrotic clinical samples." (PMID 38509574, 2024). "Secreted SPP1 has been reported to be significantly overexpressed in IPF, whereas SPP1-deficient mice models of pulmonary fibrosis exhibit reduced expression of COL1 and MMP2, as well as reduced pulmonary fibrosis." (PMID 39632841, 2024). "In the lung fibrosis environment, MMP-2 hydrolyzes the responsive peptide, releasing KGF from the nanoparticle surface and exposing the RGD motifs of ribosomal proteins." (PMID 39770584, 2024). "It was reported that dysfunction of collagen digestion enzymes (MMP2 and MMP8), and TIMP1 (a collagenase inhibitor) were associated with pulmonary fibrosis." (PMID 36717804, 2023). "The decreased number of inflammatory cells and decreased levels of total protein and inflammatory cytokines suggest that MMP-2 overexpression protects against inflammation in BLM-induced lung fibrosis." (PMID 37047672, 2023). "In a bleomycin-induced lung fibrosis rabbit model, MMP-2 expression and activity were increased at 3, 7, 14, and 28 days after bleomycin treatment in type II alveolar epithelial cells." (PMID 37675120, 2023). "Members of the MMP family, especially the gelatinases MMP-2 and MMP-9, have been implicated in pulmonary inflammation and asthma, ALI, and pulmonary fibrosis." (PMID 37763673, 2023). "The excessive increase of MMP-2 stimulates relatively more pulmonary fibrosis induced by PM2.5 than MMP-1." (PMID 37107342, 2023). "PER NPs retarget wounded alveolar epithelial cells type II (AEC II) after reacting to matrix metalloproteinase-2 (MMP-2) in Idiopathic pulmonary fibrosis (IPF) tissues." (PMID 37179259, 2023). "The present study aimed to evaluate the effect of human MMP-2 overexpression on the development of pulmonary fibrosis in a bleomycin mouse model." (PMID 37047672, 2023). "Some MMPs (MMP-3 and MMP-7) have been reported to induce EMT in lung fibrosis; however, the role of MMP-2 in EMT is unclear." (PMID 37047672, 2023).
pulmonary fibrosis (continued). "Another possible mechanism for the protective activity of MMP-2 in lung fibrosis is the inhibition of the inflammatory response." (PMID 37047672, 2023). "SARS-CoV-2 infection also leads to abnormal expression of pulmonary fibrosis related proteins, for example, MMP2, MMP8 and cathepsin were found to be upregulated and E-cadherin was downregulated." (PMID 34876129, 2021). "Combined with elevated SASP mRNA expression (including Ccl2, Cxcl10, Ccl17, Mmp2, Mmp9, and Mmp12) in sorted macrophages after irradiation, we confirmed that senescent macrophages were partly contributed to lung fibrosis." (PMID 34023858, 2021). "Gelatinases, including MMP-2 and -9, can degrade elastin molecules and are upregulated in diseases of reduced elasticity, including abdominal aortic aneurysm and pulmonary fibrosis." (PMID 30067795, 2018). "Further study is warranted to justify KL-6, SP-D and MMP-2 as confirmation of early occupational lung fibrosis in the workers exposure to dusts for the possibility of intervention or prevention of the diseases." (PMID 29149883, 2017). "Our in vitro and in vivo experiments showed that silencing β-catenin suppressed the expression of MMP2 and MMP9 at both mRNA and protein levels, which provide a possible mechanism underlying the role of Wnt/β-catenin signaling pathway in lung fibrosis." (PMID 26340635, 2015). "In this study, significant increase in lung fibrosis was observed 1 week after bleomycin administration, which parallels the increase of MMP-2, S100A4, and α-SMA protein levels." (PMID 26819949, 2015). "Our findings suggest that blockade of the Wnt/β-catenin signaling pathway by silencing β-catenin prevents the development of silica-induced lung fibrosis, which is related to the expression of MMP2 and MMP9, and secretion of TGF-β1 in the lung." (PMID 26340635, 2015). "This suggests that progressive lung fibrosis was successfully established using a single dose of bleomycin injected intratracheally and that MMP-2 in fibroblasts is involved in the ECM deposition in lung." (PMID 26819949, 2015). "Doxycycline is a potent MMP inhibitor which is able to reduce MMP-2 and MMP-9 mRNA expression and MMP-2 production in vitro and thereby attenuates collagen accumulation in pulmonary fibrosis." (PMID 24675764, 2014). "MMP-2 (or gelatinase A, 72 kDa) is well described in pulmonary fibrosis, preferentially secreted by fibroblasts and epithelial cells." (PMID 21858022, 2011). "The significantly decreased BALF level of PDGF in mice of the hMMP-2 TG/BLM group compared to the WT/BLM group, observed in the current study, suggests that MMP-2 may also ameliorate lung fibrosis by regulating the expression of PDGF." (PMID 37047672, 2023). "Overall, these anti-inflammatory activities may explain the beneficial effects of MMP-2 in pulmonary fibrosis." (PMID 37047672, 2023). "Overall, this suppressive activity on CTGF and PDGF expression may also explain, at least in part, the beneficial effects of MMP-2 in pulmonary fibrosis." (PMID 37047672, 2023). "A previous study, showing that high lung tissue levels of MMP-2 associated with the administration of human umbilical cord endothelial cells reduce BLM-induced lung fibrosis, suggests the beneficial effects of MMP-2 in lung fibrosis." (PMID 37047672, 2023). "Bleomycin‐induced pulmonary fibrosis in a rat model showed that MMP‐2 and ‐9 may have important roles in the early phase of the disease." (PMID 33274549, 2021). "This could imply that the elevations in circulating MMP1 and MMP2 expression we observed in patients with IPF are a failed attempt to control lung fibrosis." (PMID 32171287, 2020). "It has also been suggested that, in pulmonary fibrosis, MMP-9 is linked to inflammatory-induced tissue remodeling, while MMP-2 may be associated with impaired tissue remodeling, leading to abnormal collagen deposition and interstitial fibrosis." (PMID 32429399, 2020).
pulmonary fibrosis (continued). "Increased levels of lysyl oxidase (LOX), an amine oxidase critical for the initiation of collagen and elastin cross-linking, increased mRNA levels of collagen type I (Col1a2), collagen type III (Col3a1) and matrix metalloproteinase (Mmp2) have been reported in murine models of lung fibrosis." (PMID 24204629, 2013). "Thus, it is likely that MMP-2 plays a less significant role in pulmonary fibrosis under our experimental conditions." (PMID 22911824, 2012). "MMP-2 is another gelatinase involved in the pathogenesis of lung fibrosis." (PMID 20949050, 2010). "We therefore suggest that epimorphin expression in early fibrotic lesions in the lungs of patients with NSIP may contribute to the repair process in pulmonary fibrosis, in part by inducing MMP-2 expression." (PMID 15651999, 2005). "The results showed that the salidroside could up-regulate TIMP-1 and reduce the expression of MMP-2, and the degree of lung tissue lesions, suggesting that the salidroside could inhibit the process of pulmonary fibrosis by regulating the balance of MMP-2/TIMP-1." (PMID 39770545, 2024). "In addition, an anti-integrin-β3 antibody suppressed the inhibitory activity of active hMMP-2 on BLM-induced apoptosis of A549 alveolar epithelial cells, suggesting a role for the integrin-β3/phosphatidylinositol-3′ kinase pathway in the inhibitory activity of MMP-2 in BLM-induced lung fibrosis." (PMID 37047672, 2023). "Therefore, the modulatory activity of pro-apoptotic and anti-apoptotic factors may be another explanation for the protective action of MMP-2 in pulmonary fibrosis." (PMID 37047672, 2023). "However, QLJP inhibited the TGF-β1/Smad2 signaling pathway, down-regulated the expression levels of α-SMA, COL1A1, MMP2, and improved pulmonary fibrosis and pulmonary arteriole remodeling induced by low-temperature exposure to play a role in the prevention and treatment of PAH." (PMID 36611616, 2022). "Our study showed that HPS2-mice had elevated transcript levels of MMP2 and MMP9, while broad upregulation of MMP2, -3, -8, -9, -12, and -14 transcripts was evidenced in the HPS1-mice, suggesting that the pathogenesis of pulmonary fibrosis might differ in the different HPS mutations." (PMID 32485920, 2020). "MMP-2 was also up-regulated and activated in regenerated alveolar epithelial cells, which may lead to elongation and migration of these cells for repair of pulmonary fibrosis." (PMID 15651999, 2005). "Hereby the current study provides an insight on the role of miR-200a in regulating MMP-2 and MMP-9 in bleomycin (BLM)-induced lung fibrosis using both in vitro (A549 cells) and in vivo (C57BL/6 mice) models." (PMID 42004996, 2026). "Rapamycin likely alleviates the progression of sepsis-induced pulmonary fibrosis by downregulating the expression of TGF-β1, α-SMA, MMP-2, and TIMP-1, thus protecting the lung." (PMID 40332776, 2025). "In pulmonary fibrosis research, the activation of Nuclear Factor Kappa B (NF-κB)/NLRP3 signaling induces the upregulation of MMP2/9 expression." (PMID 38992615, 2024). "MMPs/TIMPs are the main enzyme system regulating ECM degradation, and an imbalance between MMP-2 and TIMP-1 expression is a key link in the onset and progression of pulmonary fibrosis." (PMID 39770545, 2024). "Therefore, we hypothesized that MMP-2 overexpression would accelerate lung fibrosis progression." (PMID 37047672, 2023). "MMP-2 expression is also increased in patients with ILD, suggesting its potential implication in the pathogenesis of pulmonary fibrosis." (PMID 37047672, 2023). "Of note, DOT1L depletion in vivo markedly inhibited the protein expression levels of bleomycin-induced pulmonary fibrosis markers (FN, CTGF, α-SMA, Collagen I/III, and MMP2/9)." (PMID 35039472, 2022). "The results showed that levels of fibrosis markers (fibronectin (FN), matrix metalloproteinase 9 (MMP9), MMP2, connective tissue growth factor (CTGF), and Collagen I) significantly increased in bleomycin-induced lung fibrosis." (PMID 35039472, 2022).